CRP (C-reactive protein)
Diseases named in the same sentence as CRP in open-access papers (continued):
Sharing a sentence is not in itself a finding about the gene and the disease.
Sepsis (continued). "First, the comparison of NEUT-RI values with those of PCT and CRP in the early stages of sepsis onset, particularly in the emergency department or ward, was not consistently feasible." (PMID 38667467, 2024). "The most studied biomarkers in infection and sepsis are C-reactive protein (CRP) and procalcitonin (PCT)." (PMID 38534707, 2024). "Based on the study results, it can be concluded that there is an increasing trend in the CRP-to-platelet ratio in neonates with clinical signs of sepsis." (PMID 39006693, 2024). "Irisin at sepsis onset exhibited a good discriminating ability for sepsis and septic shock, similar to the well-established biomarkers CRP and procalcitonin." (PMID 38540711, 2024). "A strength of this study was that extended CBC parameters such as MDW and NLR, in addition to CRP and PCT, were used as readily available and beneficial diagnostic tools for the early detection and identification of sepsis following cardiac surgery." (PMID 39336599, 2024). "Procalcitonin, C-reactive protein, and lactate are a few examples of biomarkers that have been thoroughly investigated in sepsis and have demonstrated promise for directing antibiotic therapy and forecasting results." (PMID 39189251, 2024). "The elevation of CRP, an acute-phase protein synthesized by the liver, is triggered by pro-inflammatory cytokines, reflecting the systemic inflammatory response in sepsis." (PMID 39272757, 2024). "While routine imaging and laboratory tests such as CRP and procalcitonin monitor sepsis, they fall short in specifically identifying septic encephalopathy." (PMID 39201697, 2024). "More cardio-metabolic traits were identified to be correlated to the sepsis onset such as CRP (rg = 0.37, p = 0.035), type 2 diabetes (rg = 0.33, p < 0.001), HDL (rg = − 0.41, p < 0.001), and coronary artery disease (rg = 0.43, p < 0.001)." (PMID 38459230, 2024). "Guidelines from organizations like the Surviving Sepsis Campaign (SSC) emphasize CRP as a crucial biomarker in the diagnosis and management of sepsis." (PMID 39201697, 2024). "The use of biomarkers such as PCT or C-reactive protein has the potential to improve the therapeutic management of patients with infections and sepsis." (PMID 38775503, 2024). "Sepsis workup showed an increase in serum C-reactive protein (CRP) levels and Acinetobacter baumanii grew inthe blood culture (BD BACTECTM Blood Culture Media)." (PMID 40584606, 2024). "In the current study, PLAC8 expression in total granulocytes rivaled the discriminatory performance of CRP, showing a twofold larger increase in sepsis than CRP." (PMID 39434093, 2024). "An investigation involving prepubertal children admitted to ICUs for sepsis revealed higher maximum white blood cell and neutrophil counts, lower pH, and higher C-reactive protein (CRP) levels in women." (PMID 38835761, 2024). "Specifically, CRP has demonstrated a favorable discriminative capacity for predicting mortality in children with sepsis beyond 6 months in the PICU." (PMID 39113822, 2024). "A study, performed in adult patients presenting to the ED and with suspected sepsis demonstrated that calprotectin was superior to CRP, procalcitonin and neutrophil/lymphocyte ratio in predicting the need for transfer to the ICU and other higher level of care." (PMID 38786153, 2024). "They found that IL-6 and procalcitonin were more predictive of sepsis severity and mortality compared to CRP." (PMID 39063926, 2024). "This study aims to assess nCD64 as a biomarker for sepsis and compare its diagnostic accuracy with total leukocyte count (TLC), C-reactive protein (CRP) levels, and blood culture sensitivity in adult patients." (PMID 39429998, 2024). "nCD64 has proven to be a highly sensitive and specific biomarker, outperforming TLC, CRP levels, and blood culture sensitivity tests in diagnosing sepsis." (PMID 39429998, 2024).
Sepsis (continued). "Our nomogram, including CHD, LYMP, NLR, RDW, lactic acid, PT, CRP, PCT, Tbil, ALT, and IL6, exhibits good performance for predicting mortality risk in adult sepsis patients." (PMID 38765257, 2024). "In contrast, clinical samples have demonstrated that measuring CRP in cord blood can effectively predict neonatal complications such as sepsis and infections, as well as maternal complications like amniotic infection and funisitis." (PMID 39209009, 2024). "Several protein biomarkers have already been proposed as prognostic markers of sepsis, such as CRP, lipopolysaccharide binding protein, PCT, or cytokines such as tumor necrosis factor-α and interleukin-6." (PMID 39335614, 2024). "In our study, the most sensitive markers for sepsis prediction were CRP (81.75%) and MDW (81.7%), whereas the most specific markers were MDW, MNV, and MMV, with 100% specificity for each." (PMID 39776743, 2024). "The ratio of CRP to platelet count is a better tool for assessing neonatal sepsis as it accounts for sepsis patients' inflammatory and coagulation status." (PMID 39006693, 2024). "It seems to have a greater predictive value than CRP alone in sepsis or septic shock, stroke, and postoperative conditions." (PMID 38791046, 2024). "These include markers indicative of sepsis' hyper-inflammatory phase, such as pro-inflammatory cytokines and chemokines, and proteins like C-reactive protein (CRP) and procalcitonin." (PMID 39776708, 2024). "C-reactive protein (CRP): CRP has been studied as a biomarker for sepsis, but its predictive utility is limited." (PMID 39130839, 2024). "The CRP assay yielded noteworthy findings, with positive results obtained in 40 (55.3%) patients with confirmed sepsis and 31 (44.7%) patients with probable sepsis." (PMID 38654771, 2024). "Guidelines from the Dutch Royal College of Paediatricians (NVK) recommended the use of CRP in the clinical management of meningitis, fever, sepsis in children, and neonatal sepsis." (PMID 38504318, 2024). "Regarding the association between sepsis accompanied by jaundice and neonatal sepsis complication versus age, sex, CRP, and blood culture, we found that sepsis accompanied by jaundice affected a considerable number of patients." (PMID 38654771, 2024). "Significant differences (p < 0.05) were observed for age, CCI, NLR, PCT_Delta, CRP_Delta, LAC_Base, LAC_Delta, and SOFA_Base, suggesting their potential value in predicting the outcome of sepsis." (PMID 39272757, 2024). "Classically, procalcitonin (PCT) and C-reactive protein (CRP) have been prominent targets as candidate sepsis biomarkers." (PMID 39003476, 2024). "This indicates that combined monitoring of blood lactate, PCT, and CRP levels can predict the severity and prognosis of neonatal sepsis patients." (PMID 38947447, 2024). "Elevated levels of procalcitonin (PCT) and C-reactive protein (CRP) are commonly observed in sepsis." (PMID 38947447, 2024). "As expected, the levels of sepsis-associated indicators including ALT, CRP, BUN, and creatinine (CREA2) were lower in TREM2–/– mice." (PMID 39405126, 2024). "High levels of both CRP and PCT are associated with increased mortality risk, highlighting their significance in early sepsis management." (PMID 39469363, 2024). "Previous research is consistent with our findings, confirming the role of elevated CRP as a predictor of sepsis." (PMID 39064542, 2024). "Patients who developed sepsis had higher leucocyte counts and CRP levels at admission in both age groups, whereas the difference was significant only for patients < 65 years (p = 0.04 and 0.04, respectively)." (PMID 38541796, 2024). "Sepsis diagnosis is based on the presence of certain biomarkers in the patient’s blood, for instance, C-reactive protein (CRP), procalcitonin (PCT), tumor necrosis factor-alpha (TNF-α), high-mobility group box 1 protein (HMGB-1), and interleukin-6 (IL-6)." (PMID 38920613, 2024).
Sepsis (continued). "Nevertheless, commonly used biomarkers, including C-reactive protein (CRP) and procalcitonin, have been proven inaccurate in detecting sepsis in previous meta-analyses." (PMID 38711008, 2024). "Biomarkers such as procalcitonin (PCT) and C-reactive protein (CRP) have been widely used to aid in the diagnosis and management of sepsis, as they are known to increase in response to bacterial infections." (PMID 38172766, 2024). "CRP levels were also demonstrated to decrease in patients with initial sepsis progressing to septic shock during the course of ICU treatment." (PMID 37204560, 2024). "Their study concluded that CRP is useful as a biomarker regarding inflammation, but its efficacy as a marker for predicting sepsis course remains uncertain." (PMID 38684973, 2024). "We measured the CRP levels at baseline and over subsequent days (day 1, day 3, and day 7) in patients with sepsis." (PMID 39507174, 2024). "The average CRP level in a healthy person is 2 mg mL−1, and for sepsis patients it increases more than 1000 times." (PMID 38920613, 2024). "With an area under the curve (AUC) of 0.861 on day 7 and 0.833 on day 10, the PCT revealed a superior AUC than the CRP (AUC 0.440–0.652) with regard to the discrimination between patients with sepsis and septic shock." (PMID 37204560, 2024). "The AUCs for sepsis of CRP and PCT were 0.62 (95%CI 0.54–0.69; p = 0.008) and 0.69 (95%CI 0.59–0.78; p < 0.001), respectively." (PMID 38337856, 2024). "Studies conducted worldwide, particularly in surgical contexts, reported similar limitations in the predictive utility of CRP in sepsis." (PMID 39507174, 2024). "Laboratory findings detailed pancytopenia and were suggestive of neutropenic sepsis with a high C-reactive protein (CRP) of 208, white blood cell count (WBC) of 1.5, neutrophil of 0.8, platelets of 129, and haemoglobin (HB) of 8.7." (PMID 39280358, 2024). "Other biomarkers that have been used in the diagnosis of sepsis are c-reactive protein (CRP), procalcitonin (PCT), and interleukin-6 (IL-6)." (PMID 38396935, 2024). "In the current study, we demonstrated that the CRP and PCT on hospital admission were weakly associated with the incidence of sepsis after trauma, which was consistent with previous studies." (PMID 39624089, 2024). "A recent study that included 2,492 patients with sepsis showed that age, fibrinogen, CRP, SOFA score, congestive heart failure, and dobutamine use were used as risk variables to create a nomogram model, achieving an AUC of 0.861." (PMID 39030470, 2024). "At 8 days old, the infant presented signs of septicemia and had an elevated C-reactive protein (CRP) level." (PMID 39585019, 2024). "As an inflammatory marker, CRP serves as an important comparator of the index test; however, in two studies, it was also used for being the reference standard to diagnose sepsis." (PMID 38671704, 2024). "Procalcitonin (PCT) and C-reactive protein (CRP) are commonly used biological markers for inflammation and sepsis." (PMID 39669267, 2024). ",17,29, 30, 31 In support of this, BNP and Troponin levels are increased in patients presenting with sepsis and the elevated cardiac biomarkers correlate well with increased C-reactive protein and TNF-alpha levels." (PMID 39197405, 2024). "Neonates with MSAF, especially those with concurrent PROMs, had significantly elevated CRP levels, suggesting severe inflammation or sepsis." (PMID 39861100, 2024). "The study investigates the diagnostic and prognostic value of C-reactive protein (CRP) and procalcitonin (PCT) in patients with sepsis and septic shock." (PMID 37204560, 2024). "C-statistics revealed comparable but poor diagnostic performance for PCT on day 1 (AUC = 0.590) and poor AUC for CRP (AUC = 0.440) to discriminate patients with septic shock from those with sepsis (p for AUC difference = 0.001)." (PMID 37204560, 2024).
Sepsis (continued). "There are three biomarkers that aid in diagnosing sepsis: i) C-reactive protein (CRP), ii) pancreatic stone protein (PSP) and iii) procalcitonin (PCT)." (PMID 39416748, 2024). "MDSC was a diagnostic biomarker comparable to CRP and PCT, in infection and sepsis, including for distinguishing sepsis from infection." (PMID 38609858, 2024). "Ferritin, along with CRP can be used together in order to distinguish groups of neonates with sepsis who have different mortality risks and systemic inflammation responses." (PMID 39829727, 2024). "Traditional biomarkers such as CRP, PCT, leukocyte count, neutrophils, and platelets have diagnostic limitations regarding neonatal sepsis." (PMID 39829727, 2024). "For instance, low absolute lymphocyte counts predict postoperative sepsis and bacteremia better than conventional markers like CRP." (PMID 39130839, 2024). "On day five, with CRP being elevated, the sepsis management continued with broad-spectrum antibiotics, leading to the normalization of inflammatory markers and resolution of clinical signs of sepsis." (PMID 39070423, 2024). "The ROC curve depicts the diagnostic efficacy of CRP and PCT in diagnosing sepsis, showcasing their capacity to differentiate between individuals with sepsis and those without." (PMID 39469363, 2024). "Among the biomarkers investigated extensively and utilized in severe sepsis patients, C‐reactive protein (CRP) and procalcitonin (PCT) stand out as the most prominent." (PMID 38708489, 2024). "LCAT activity was negatively correlated with CRP in sepsis, consistent with the positive correlation between FC and CRP." (PMID 39311203, 2024). "Leucocytes and CRP: Upon admission, patients who developed sepsis tended to have significantly greater leucocyte counts in the age group < 65 years and higher CRP values in both age groups." (PMID 38541796, 2024). "In our post hoc analysis, higher Ang-II concentrations were detected in ICU patients with higher CRP levels, a positive fluid balance, and impaired kidney function in the initial phase of sepsis." (PMID 39595003, 2024). "Serum suPAR, together with other inflammatory markers IL-6, IL-16, CRP, and CCL3, was associated to the severity of sepsis-induced acute kidney injury." (PMID 39540961, 2024). "Among these, sepsis or high C-reactive protein level, oral anticoagulant medication, and pre-analytical artifacts were likely responsible in most patients." (PMID 38713343, 2024). "For predicting sepsis, defined as multi-organ dysfunction and infection, and 30-day mortality calprotectin showed a similar performance to procalcitonin and CRP." (PMID 38755564, 2024). "Further analysis indicated that the prognostically unfavorable factors in sepsis were age, O2− and CRP concentrations, and the GDI." (PMID 39594227, 2024). "For example, a recent study looked at the correlation between gut microbiota, C- reactive protein and sepsis, and suggested that this protein has a potential role as a mediator in facilitating the impact of some bacterial species on sepsis." (PMID 38933024, 2024). "For participants with sepsis, the mean CRP level was 98.5 mg/L (SD: 38.5), while those with septic shock had a mean CRP of 115 mg/L (SD: 38.5), with a significant p-value of 0.001." (PMID 39469363, 2024). "Other laboratory indicators, such as alkaline phosphatase (ALP), C-reactive protein (CRP), albumin (ALB) and lactate (LAC), are risk factors for SRLI in patients with sepsis." (PMID 39712312, 2024). "Other studies suggest CRP is a confounding factor in identifying sepsis in burn patients as the chronic inflammatory process is a normal response to burn trauma." (PMID 38684973, 2024). "We hereby confirm previous studies, stating that CRP alone has a lower predictive value for outcome in patients with sepsis, stroke, or after surgery than CAR." (PMID 38791046, 2024). "In line, the present study suggested poor diagnostic value of both CRP and PCT with regard to blood-culture positive sepsis." (PMID 37204560, 2024).
Sepsis (continued). "P-SEP also seems to be a promising discriminant of sepsis in neonates, but further studies are needed about the three biomarkers (CRP, PCT, and P-SEP) distinguishing EOS and LOS cases (often considered together in some studies)." (PMID 38535886, 2024). "The present study comprehensively investigates the diagnostic and prognostic role of CRP and PCT in patients admitted with sepsis or septic shock." (PMID 37204560, 2024). "Based on our findings, vitamin C infusion helps improve the SOFA score and CRP level in sepsis patients." (PMID 39776708, 2024). "Other studies carried out on patients with sepsis or multiple inflammatory and respiratory problems have shown a reduction of CRP and IL-6 concentrations after n-3 FA supplementation." (PMID 38702342, 2024). "For both subcohorts, a higher mean value for CRP in sepsis than SIRS was the only statistically significant difference between these two subgroups." (PMID 39434093, 2024). "PCT was sensitive enough to detect sepsis episodes much earlier than CRP because it is detecTable 3 h after exposure, peaking by the 6 h mark." (PMID 38535886, 2024). "Procalcitonin, released from tissues in response to infection, rises more rapidly than CRP, making it an effective early marker for sepsis detection." (PMID 39347186, 2024). "The statistically significant predictors of neonatal sepsis were the white blood cell count from the first (p = 0.005) and third day (p = 0.028), and CRP values from the first day (p = 0.004)." (PMID 38255436, 2024). "An ideal marker as an adjunct to infection proxy criteria would have a high specificity to minimise the inclusion of sepsis mimics, which was the case for CRP, WBC and temperature." (PMID 38280062, 2024). "An increased concentration of C-reactive protein (CRP) in response to GPB sepsis was observed in most patients (n = 312, 90.2%)." (PMID 38517573, 2024). "In patients with sepsis, apoB-depleted plasma’s anti-inflammatory capacity correlates with disease severity and various inflammatory markers, such as the CRP level and WBC." (PMID 38603717, 2024). "Recent evidence has emerged supporting the use of the serum CRP-to-albumin ratio (CAR) as a predictor of sepsis and prognostic indicator in patients with severe burn injury." (PMID 39716257, 2024). "Several studies, including ours, have highlighted the potential of serum PCT, CRP, and PSP levels as key biomarkers for risk stratification in pediatric sepsis." (PMID 39295616, 2024). "The AUCs for sepsis of CRP and PCT were 0.83 (95%CI 0.79–0.88; p < 0.001) and 0.78 (95%CI 0.73–0.84; p < 0.001), respectively." (PMID 38337856, 2024). "Some studies that evaluated C-reactive protein, along with the total number of leukocytes, as being a biomarker used to identify newborns with sepsis, found these are still useful for evaluating neonates with suspected infection." (PMID 39829727, 2024). "The role of CRP in sepsis has been extensively studied, and it is well-established that elevated CRP levels correlate with the presence of infection and the severity of the inflammatory response." (PMID 39469363, 2024). "We also collected clinical parameters such as procalcitonin, WBC and CRP at the time of PET/CT scan to assess the degree of inflammatory or sepsis status and PET outcome." (PMID 39085535, 2024). "The baseline characteristics of the entire cohort were similar except for age, sepsis type, infection site, C-reactive protein, mechanical ventilation, and microbiology." (PMID 38816883, 2024). "It is being postulated that CRP and serum albumin are useful markers that can predict mortality in patients with sepsis." (PMID 39252713, 2024). "In this study, the three specific biomarkers (PSP, PCT and CRP) are being compared regarding the different performance of each biomarker to establish sepsis diagnosis in ICU." (PMID 39416748, 2024). "PSP is also superior to ferritin, CRP, and fibribogen in the prediction of sepsis, treatment escalation, and readmission." (PMID 38892234, 2024).